TC2N (tandem C2 domains, nuclear)
Synonyms: Tac2-N; C14orf47; MTAC2D1; FLJ36557; C2CD1; TAC2N
Tractability: No criterion of Open Targets' tractability assessment is met for any kind of drug.
Gene: Protein-coding gene on chromosome 14 (91,779,746 to 91,867,536, reverse strand). Ensembl gene ENSG00000165929.
Subcellular location: Nucleus
Subcellular location (Human Protein Atlas): Nuclear bodies; Nucleoplasm
Gene Ontology:
Cellular component: nucleus
Genetic constraint (gnomAD): Loss-of-function variants: 20 observed, 24.95 expected, observed/expected ratio (o/e) 0.8, 90% interval 0.56 to 1.16. The upper end of that interval is the gene's LOEUF score, 1.16, which puts it in group 5 of 6, group 1 being the genes least tolerant of losing a copy. Missense variants: 308 observed, 328.22 expected, observed/expected ratio (o/e) 0.94, 90% interval 0.85 to 1.03. Synonymous variants: 115 observed, 113.11 expected, observed/expected ratio (o/e) 1.02, 90% interval 0.87 to 1.19.
Homologues: Orthologues: chimpanzee TC2N (99% identical), macaque TC2N (97% identical), pig TC2N (92% identical), rabbit TC2N (89% identical), guinea pig TC2N (88% identical), mouse Tc2n (88% identical), rat Tc2n (87% identical), tropical clawed frog tc2n (63% identical), zebrafish TC2N (44% identical). Paralogues in human: SYT9 (18% identical), SYT10 (18% identical), SYT6 (18% identical), SYT3 (18% identical), SYT14 (18% identical), SYTL2 (17% identical), SYT11 (16% identical), SYTL4 (16% identical), SYT16 (16% identical), SYT7 (16% identical), SYT4 (16% identical), SYTL5 (16% identical), and 19 more.
Diseases named in the same sentence as TC2N in open-access papers:
TC2N is named in the same sentence as 23 diseases in open-access papers, as found by Europe PMC text mining. Sharing a sentence is not in itself a finding about the gene and the disease. The quoted sentences say what the papers report.
lung carcinoma (7 papers, 2019 to 2025). "Clinically, high TC2N expression was associated with lower differentiation degree (DD) in lung cancer and correlated with a poorer prognosis for patients." (PMID 39849581, 2025). "Tumor tissues of 395 lung cancer patients were subjected to tissue microarray and further assessed the associations of TC2N expression with tumor differentiation degree." (PMID 39849581, 2025). "TC2N expression is also associated with the prognosis and development of human lung cancer and breast cancer 16-18." (PMID 33403038, 2021). "In this review, we summarize recent progress in understanding the role and underlying mechanisms of TC2N in the occurrence and development of cancer, with a focus on lung cancer, breast cancer, and gastric cancer." (PMID 34925334, 2021). "Upregulated TC2N promoted tumor growth and metastasis and is associated with high histological grade, advanced clinical stage, and thus a poor clinical prognosis of lung cancer patients." (PMID 31142739, 2019). "Co-IP assays using DUSP3 antibody in stable lung cancer cell lines showed that TC2N overexpression reduced the interaction between endogenous DUSP3 and its substrates." (PMID 39849581, 2025). "Regarding the mechanism of the tumor-promoting role of TC2N in lung cancer, we showed that the interaction between DUSP3 and TC2N blocked DUSP3’s interaction with its substrates and inhibited its enzymatic activity." (PMID 39849581, 2025). "In summary, TC2N is a potential novel oncogene in lung cancer, whose expression levels are correlated with cancer progression and patient survival." (PMID 34925334, 2021). "Similar to that in lung cancer tissues, the expression of TC2N was markedly upregulated in breast cancer tissues compared with that in adjacent non-cancerous tissues." (PMID 34925334, 2021). "In summary, in contrast to its role in lung cancer cells, TC2N is a potential tumor suppressor in breast cancer." (PMID 34925334, 2021). "In another way, TC2N also can facilitate migration and invasion of lung cancer cells in vitro and promote tumor metastasis in vivo through increasing the degradation of IκB by promoting its phosphorylation, and subsequently activating NF-κB activity." (PMID 33403038, 2021). "Role of TC2N in carcinogenesis has been largely unfathomed until recently when it was identified as a novel oncogene in lung cancer." (PMID 33247676, 2020). "It has been recently reported that increased TC2N transcript expression promotes cell proliferation and inhibits tumour cell apoptosis in lung cancer." (PMID 33247676, 2020).
lung carcinoma (continued). "Together, these data further suggested that TC2N significantly promotes lung cancer cell tumorigenesis and growth in vivo." (PMID 30254375, 2019). "To obtain insight into the potential role of TC2N in lung cancer progression, we first monitored the messenger RNA (mRNA) and protein expression levels of TC2N in various lung cancer cell lines by quantitative PCR and western blotting (WB)." (PMID 30254375, 2019). "Specifically, through in vitro and in vivo assays, we demonstrated that TC2N acts as a novel oncogene by inhibiting apoptosis and promoting the proliferation of lung cancer cells." (PMID 30254375, 2019). "To further determine the expression of TC2N in lung cancer patients, we examined the levels of TC2N protein on a TMA containing 272 lung tumor tissues and 265 paired adjacent non-tumor tissues." (PMID 30254375, 2019). "Subsequently, we identified TC2N is significantly overexpressed in human lung cancer patients and is significantly correlated with clinical stage and histological grade." (PMID 30254375, 2019). "To further investigate the downstream targets involved in TC2N-mediated tumor progression, we analyzed the correlation between TC2N and other genes in lung cancer patients using The Cancer Genome Atlas (TTCGA) database." (PMID 30254375, 2019). "After analyzing the potential associations between TC2N expression and the clinicopathological characteristics of lung cancer patients, we found that TC2N expression levels were significantly correlated with clinical stage and histological grade." (PMID 30254375, 2019). "TC2N was overexpressed in a variety of lung cancer cell lines compared with HBE cells (a human bronchial epithelial cell line)." (PMID 30254375, 2019). "In the present study, we examined the expression of TC2N in human lung tumors and matching adjacent normal tissues using tissue microarray (TMA), and found that TC2N protein level was overexpressed in human lung cancer." (PMID 30254375, 2019). "Conversely, overexpression of TC2N in lung cancer cells enhanced their stemness properties." (PMID 39849581, 2025). "Overall, this study revealed a previously unknown role and mechanism of TC2N in the regulation of tumorigenesis and stemness in lung cancer cells." (PMID 39849581, 2025). "We hypothesized that TC2N may enhance the phosphorylation of these proteins by blocking DUSP3 in lung cancer cells." (PMID 39849581, 2025). "Notably, overexpression of NF-κB—both in the nucleus and cytoplasm of lung cancer cells—correlated with increased expression level of TC2N in these cells." (PMID 34925334, 2021). "Here, we first identified TC2N as a novel oncogene in lung cancer." (PMID 30254375, 2019). "Further, to explore whether TC2N is a potential prognostic factor for lung cancer, we performed Kaplan–Meier survival analysis of the 272 lung cancer patients based on their TC2N expression levels." (PMID 30254375, 2019).
lung carcinoma (continued). "Using the H460 cell line, we found that knockdown of TC2N expression significantly enhanced Dox-induced apoptosis, suggesting that TC2N may play an important role in the chemoresistance of lung cancer cells." (PMID 30254375, 2019). "In our present study, we found that TC2N is also frequently overexpressed in BC tissues, but is under expressed in adjacent normal tissues, which is coordinated with the expression pattern of TC2N in lung cancer." (PMID 31142739, 2019). "We next determined whether TC2N induces Cdk5 degradation by promoting its ubiquitination in lung cancer cells." (PMID 30254375, 2019). "Taken together, we have identified the novel functional oncogene TC2N in lung cancer." (PMID 30254375, 2019). "Although TC2N has proven to be an oncogene in lung cancer, its biological function and molecular mechanisms in other cancer still remains unclear." (PMID 31142739, 2019). "Thus, similar to lung cancer, TC2N potentially functions as an oncogene in gastric cancer." (PMID 34925334, 2021). "Mechanistically, overexpression of TC2N significantly inhibited apoptosis, promoted cell proliferation, and increased migration and invasion of tumor cells in vitro; in contrast, knockdown of TC2N promoted apoptosis and inhibited proliferation of lung cancer cells." (PMID 34925334, 2021). "Furthermore, knockdown of TC2N in tumor tissues resulted in an increase in apoptotic cells, supporting the hypothesis that TC2N overexpression promotes tumorigenesis and growth of lung cancer tumors in vivo." (PMID 34925334, 2021). "However, unlike that in lung cancer, upregulated TC2N was associated with good prognosis and overall survival." (PMID 34925334, 2021). "Thus, we explored whether TC2N can regulate cell cycle and apoptosis of lung cancer cells." (PMID 30254375, 2019). "Moreover, TC2N may be a potential target and clinical marker for lung cancer therapy." (PMID 30254375, 2019).
breast carcinoma (6 papers, 2019 to 2024). "Previously, we preliminarily reported that TC2N mediates the PI3K-Akt signaling pathway to inhibit tumor growth of breast cancer (BC) cells." (PMID 38167440, 2024). "To test TC2N inhibitory function on fatty acid synthesis in vivo, we injected E0771 cells into the mammary fat pad of nude mice to produce tumor models of breast cancer in situ and further observed lipid deposition by oil red O staining." (PMID 38167440, 2024). "TC2N is also frequently overexpressed in breast cancer, but interestingly, high TC2N expression predicts favorable prognosis in breast cancer." (PMID 33403038, 2021). "Subsequently, the same group reported TC2N as a potent suppressor of PI3K-AKT signaling in breast cancer, suggesting its tumour suppressor activity in breast cancer." (PMID 33247676, 2020). "While these recent (and only) studies have highlighted TC2N as a potential player in lung and breast cancers, its role in other tumour types remains un-addressed." (PMID 33247676, 2020). "Upregulation of TC2N significantly restrains breast cancer cell proliferation in vitro and tumor growth in vivo." (PMID 31142739, 2019). "Notably, TC2N has been identified as an oncogene in lung and gastric cancer but as a tumor suppressor gene in breast cancer." (PMID 34925334, 2021). "Subsequently, the same group reported tumour suppressor role of TC2N in breast cancer." (PMID 33247676, 2020). "Subsequently, a tumour suppressor role of TC2N was reported in breast cancer." (PMID 33247676, 2020). "However, TC2N was found to play a completely different role in breast cancer." (PMID 33403038, 2021). "Further study proved that upregulation of TC2N obviously restrained breast cancer cell proliferation in vitro by blocking AKT signaling in a PI3K dependent and independent way, suggesting that TC2N may be a tumor suppressor in breast cancer." (PMID 33403038, 2021).
gastric cancer (3 papers, 2021 to 2022). A primary or metastatic malignant neoplasm involving the stomach. "It was revealed that high TC2N expression was also associated with poor survival of gastric cancer patients after adjusting for tumor size, depth of tumor invasion, lymph node metastasis and distant metastasis (HR = 1.616; 95%CI: 1.121-2.332, p= 0.010)." (PMID 33403038, 2021). "In vitro, TC2N knockdown significantly inhibited the proliferation of gastric cancer cells, while TC2N overexpression promoted the growth of these cells." (PMID 34925334, 2021). "We found that both the mRNA and protein levels of TC2N were markedly elevated in gastric cancer tissues in comparison with adjacent normal gastric tissues." (PMID 33403038, 2021). "Similar results were observed in vivo where downregulation of TC2N inhibited the migration and invasion of gastric cancer cells, whereas overexpression had the opposite effect." (PMID 34925334, 2021). "TC2N expression is upregulated in different types of cancers, including lung, breast, and gastric cancers." (PMID 34925334, 2021). "However, the role TC2N playing in gastric cancer is still unclear." (PMID 33403038, 2021). "Thus, TC2N expression can serve as a prognostic biomarker for patients with gastric cancer." (PMID 33403038, 2021). "The mRNA level of TC2N in GC tissues and normal gastric tissues from the GEPIA database also showed an increase in gastric cancers compared with normal gastric tissues." (PMID 33403038, 2021). "However, the status of TC2N expression and its significance in gastric cancer (GC) is still unclear." (PMID 33403038, 2021). "Furthermore, we also detected the prognostic indicator effect of TC2N expression in early (TNM stage I and II) and advanced (TNM stage III and IV) gastric cancer, respectively." (PMID 33403038, 2021).
adrenal pheochromocytoma (1 paper, 2020). "Amongst the tumours with low overall TC2N expression, THCA showed significant downregulation of TC2N in all histologic subtypes compared to controls while in PCPG only Paraganglioma;extra adrenal pheochromocytoma subtype showed significant downregulation of TC2N compared to the controls." (PMID 33247676, 2020).
cholangiocarcinoma (1 paper, 2020). A carcinoma that arises from the intrahepatic biliary tree (intrahepatic cholangiocarcinoma) or from the junction, or adjacent to the junction, of the right and left hepatic ducts (hilar cholangiocarcinoma). "TC2N transcription was significantly higher in cholangiocarcinoma (CHOL), ovarian serous cystadenocarcinoma (OV), rectal adenocarcinoma (READ), stomach adenocarcinoma (STAD) and thymoma (THYM)." (PMID 33247676, 2020).
glioma (1 paper, 2020). A benign or malignant brain and spinal cord tumor that arises from glial cells (astrocytes, oligodendrocytes, ependymal cells). "Poor prognosis was associated with higher TC2N mRNA levels in pancreatic-adenocarcinoma and brain-lower-grade-glioma and lower TC2N mRNA levels in kidney-renal-clear-cell-carcinoma, mesothelioma, sarcoma and skin-cutaneous melanoma." (PMID 33247676, 2020).
paraganglioma (1 paper, 2020). A benign or malignant neoplasm arising from paraganglia located along the sympathetic or parasympathetic nerves. "TC2N transcription was significantly lower in pheochromocytoma and paraganglioma (PCPG), skin cutaneous melanoma (SKCM), thyroid carcinoma (THCA) and uterine carcinosarcoma (UCS)." (PMID 33247676, 2020).